CD4 (CD4 molecule)
Diseases named in the same sentence as CD4 in open-access papers (continued):
Sharing a sentence is not in itself a finding about the gene and the disease.
lymphoma (continued). "Research demonstrated that anti-CD20 mAb, such as rituximab, could achieve a long-lasting “vaccinal effect” with the presence of both CD4+ and CD8+ T cells, indicating the potential value of QHF as an add-on therapy to the R-based therapy for lymphoma patients." (PMID 35818037, 2022). "A total of 3 of the 25 cases, all included in the C category, could not be evaluated for CD4+ T-cell counts categories, as patients had not performed CD4+ counts in the eligible period for the study (3 months before/3 months after lymphoma diagnosis)." (PMID 36551614, 2022). "However, HIV control was improved among PLWH and lymphoma in the post-UART period but without significant improvement in baseline CD4 T-cell counts." (PMID 36048901, 2022). "However, in the four cases with interface dermatitis patterns in our study, the lymphoma cells were negative for both CD4 and CD8." (PMID 36135102, 2022). "Malignant T cells emerging in SNF5fl/f, CD4-Cre+ mice, despite their proliferative capacity in vivo, undergo rapid spontaneous apoptosis when cultured ex vivo, suggesting that the provision of extrinsic growth and survival signals by constituents of the TME support lymphoma growth." (PMID 36970721, 2022). "TH2-polarized CD4+ T cells secrete cytokines that can limit CTL differentiation and proliferation such as IL-10 and IL-4, while CD4+ TRegs (FOXP3+) have significant immunosuppressive functions through various mechanisms and their pro-tumor role has been described in both solid tumors and lymphomas." (PMID 33842331, 2021). "We propose that lack of intrafollicular CD4 + T cells can be considered as a surrogate biomarker of immune escape in a manner analogous to the case of CREBBP mutant lymphomas, which indeed benefit from HDAC3-selective inhibitors to promote immune-related activities." (PMID 34267181, 2021). "MDV infection leads to development of CD4+ T cell lymphoma in infected chickens, thus it is possible that the MDV-induced COX2/PGE2 pathway may contribute to tumorigenesis of MDV by suppressing immune response against MDV-induced CD4+ lymphoma cells." (PMID 35003129, 2021). "In classic Hodgkin’s Lymphoma, where MHC-I expression is lost but MHC-II expression is intact, CD4+ T cell infiltration in tumor was correlated with better prognosis in patients and showed improved efficacy of a PD-1 blocking antibody in MHC-II-expressing lymphoma." (PMID 34012451, 2021). "T-lymphocytes—including CD4+ T-helper cells (Ths), CD4+/FOXP3+ regulatory T-cells (Tregs), and CD8+ cytotoxic T-lymphocytes (CTLs)—are fundamental for immune surveillance and disease progression and, thus, continue to be studied extensively in essentially all lymphoma subtypes." (PMID 33804869, 2021). "Blinded analysis confirmed that both the proportion of IL-8+ naïve CD4+ T cells and the proportion of IL-8+ naïve CD8+ T cells were markedly elevated in patients with thymomas, compared to healthy controls or patients with thymic cysts, teratomas, and lymphomas in the validation set." (PMID 32985506, 2020). "Studies of CD19 CAR-T cells in an NSG mouse model of lymphoma have shown that TN and TCM produce a superior CAR-T product to TEM in terms of cytokine production (CD4+) and cytotoxicity (CD8+), and the potency of CD8+ CAR-T cells is enhanced by their production in the presence of CD4+ T cells." (PMID 31093282, 2019). "Unexpectedly, these lymphoma cells were immuno-reactive with CD8 but not with CD4." (PMID 29788970, 2018). "Lymphoma development may be due to the lacking tumor suppressive function of STK4 or the perturbed immune surveillance due to the lack of CD4+ T cells." (PMID 30386345, 2018). "However, the onset of disease was not significantly different between Eμ‐MYC/Vav‐BFL1 mice that harboured CD19−B220+CD4+ progenitor cell lymphomas in their thymus and those that did not (Kaplan–Meier plot)." (PMID 29498802, 2018).
lymphoma (continued). "Interestingly, immunohistochemical staining revealed that these lymphoma cells were negative for CD4 but positive for CD8." (PMID 29788970, 2018). "In this study, we demonstrated an elevated frequency of CD4+CD25+FoxP3+CD127lo Treg in PB, BM and involved lymphatic tissues from patients with B-cell NHL, and we also showed that these cells could be potently induced by lymphoma B cells in vitro." (PMID 22174855, 2011). "Degranulation assays restricted to CD4-MHCII interactions indicated the ability for degranulation and cytotoxicity, while isolated and stimulated TFK cells could induce apoptosis in FL and DLBCL B cells, highlighting their potential role in anti-lymphoma immunity." (PMID 41030456, 2025). "Although most of our children were using ART/cART at lymphoma diagnosis, they did not start treatment with cART as the first antiretroviral therapy but with suboptimal treatments, which could explain the low cohort CD4+ T-cell counts at lymphoma diagnosis." (PMID 37190220, 2023). "It is known that HIV-positive children are at higher risk of developing lymphoma, as HIV itself causes immunologic and cellular changes that increase susceptibility to other viruses and enhance their oncogenic potential, irrespective of anti-retroviral (ART) administration and CD4+ count." (PMID 34945274, 2021). "In addition, compared with unselected T cells and CD8 or CD4 T cells alone, CAR T cells consisting of CD4 T cells derived from the naive CD4 T cell pool and CD8 T cells derived from central memory CD8 T cells at a 1:1 ratio, showed superior efficiency in mouse lymphoma model." (PMID 29163850, 2017). "Moreover, PDE4B was found to be highly expressed in CD4+ lymphoid cancer cells, which suggests that it may represent a physiological role unique to the CD8+ and lymphoid cancer cells and thus might represent a target for pharmaceutical intervention for certain lymphoid diseases." (PMID 23451206, 2013). "Moreover, we demonstrate a significant increase of naïve CD4+CD127lowFOXP3+ Treg cells in peripheral blood of cancer patients while we could not detect an increase in lymph node biopsies of lymphoma patients." (PMID 21904560, 2011). "Unlike CD4+ Tfr cells, which are predominantly enriched in FL20, CD8+ Tfr cells appear to play an important role in both lymphoma subtypes, potentially contributing to immune suppression within germinal center‐like microenvironments." (PMID 41190308, 2025). "Both lymphomas contained significantly more FOXP3+ Tregs, which was reflected in more CD4+FOXP3+CXCR5+PD-1+ TFR cells among CD4+ T cells, but not among Tregs for FL." (PMID 41030456, 2025). "Her compromised immune system secondary to the lymphoma and HIV infection must have exposed her to histoplasmosis although the CD4+ cell count was not remarkably low." (PMID 39399793, 2024). "The number of mice that developed lymphomas in the CD4-depleted groups was not higher in those treated with SQV or DMBA, indicating the CD4 depletion led to lymphoma development." (PMID 39339897, 2024). "LYWS-1061 submitted by Megan Fitzpatrick lacked sufficient TFH marker expression (only CD4 and ICOS) to diagnose TFH lymphoma." (PMID 37500795, 2023). "At variance, in mice where lymphoma did not grow, we observed very few exhausted T cells (PD-1+TIM3+CD4+ were <2% and PD-1+TIM3+CD8+ were <1% of all gated cells)." (PMID 37048617, 2023). "We analyzed by flow cytometry the percentage of exhausted CD3+CD4+ and CD3+CD8+ T cells along with PD-1+TIM3+ subpopulations in the spleen of lymphoma-engrafted and not engrafted mice." (PMID 37048617, 2023). "During the 7-year study period, 91 PLWH were diagnosed with IP, with three being excluded due to the lack of baseline CD4 count and PVL value (n = 1), lymphoma on chemotherapy (n = 1), and no initiation of ART within 30 days (n = 1)." (PMID 36877061, 2023).
lymphoma (continued). "One HIV-positive SARS-CoV-2 naïve donor with a low CD4 T cell count of 40 cells/μL on ART, and one individual with relapsed lymphoma, both had no detectable humoral and cellular responses after 2 or 3 doses of mRNA vaccine." (PMID 36380764, 2022). "The current study demonstrated no positive role of the panel of immunochemistry CD4, CD8, CD68, and MMP with the overall survival of the lymphoma prognosis." (PMID 35083113, 2022). "Thus, vaccination with alpha-galactosylceramide-loaded A20 lymphoma cells elicited effective antitumor immunity against tumor challenge, and depletion as well as adoptive transfer studies revealed an exclusive role of conventional CD4+, but not CD8+, T cells in mediating antitumor immunity." (PMID 36159781, 2022). "Flow cytometry classified the lymphoma as a double-negative phenotype of T-cell lymphoma (CD3+ and CD5+, but CD4- and CD8-) present in the duodenum and liver and suspected in the spleen which has previously not been reported in cats." (PMID 34925932, 2021). "In that case, lymphoma cells were immunohistochemically positive for CD3, but the results of immunohistochemical staining for CD4, CD8, and CD56 were not described." (PMID 33939308, 2021). "We compared the gene expression profile of sorted CD4+GFP+ lymphoma cells with naive CD4+ T cells, CD4+GFP− non-malignant stromal T cells from the lymphoma and CD4+GFP+FYNG2A-TRAF3IP2-expressing T cells." (PMID 34140493, 2021). "The lymphoma cells express CD2 and CD3e, but usually not CD3s or other T-cell markers (CD4, CD5, and CD8)." (PMID 34702349, 2021). "Immunophenotypically, the lymphoma cells were positive for CD30 (cytoplasmic with a Golgi pattern) and CD25 and did not express CD3 and CD8, but were positive for CD4, and a subset of the lymphoma cells were granzyme-positive." (PMID 32560455, 2020). "Culture of the lymphoma cells in simulated microgravity (SMG), and not Static conditions, restored the CD4+ T cell response and augmented CD8+ T cell-mediated destruction of the cancer cells in vitro and in vivo." (PMID 31602007, 2019). "The frequencies of PD-1+LAG-3+ heavily exhausted T cells among CD4+ and CD8+ T cells was higher in the blood of cattle with B-cell lymphoma over that of BLV-uninfected and BLV-infected cattle without lymphoma." (PMID 29914540, 2018). "Negativity for leukocyte common antigen (LCA) and other lymphoid markers (CD3, CD20, CD7, CD4, CD79a, CD30, CD68, PAX5, ALK1, and TdT) rules out malignant lymphoma." (PMID 29914385, 2018). "Correspondingly, CD4+ and CD8+ T cells from HIV+ patients with lymphoma were not functional after polyclonal stimulus (PMA + ionomycin; data not shown)." (PMID 30337929, 2018). "Although there was no statistical difference of frequency of CD4+PD-1+ T cells between tonsil and lymphoma patients, we did find that the numbers of CD8+PD-1+ T cells were significantly higher in lymphoma tissues than tonsils." (PMID 28977875, 2017). "Our study did not allow for CD4 count analysis as it was not undertaken in the HIV clinic setting, however, a lymphoma diagnosis gives a patient an HIV WHO stage of IV which necessitates ART initiation." (PMID 28292305, 2017). "To our surprise, we did not observe any difference in lymphoma growth after immunization with full-length c-MYC protein and subsequent challenge with 291 PC cells, even though we observed c-MYC-reactive CD4+ and CD8+ T-cells ex vivo." (PMID 24130880, 2013). "The frequencies of both PD-1+ CD4+ T cells in blood and lymph node and PD-1+ CD8+ T cells in lymph node were higher in BLV-infected cattle with lymphoma than those without lymphoma or control uninfected cattle." (PMID 23876077, 2013). "Alternatively, the inability to completely rule out KS and lymphoma localised in the lung, which contributed up to 50% of lung neoplasms in the pre-cART era, could lead to erroneous interpretations, given the strong associations of these two AIDS-defining cancers with declining CD4+ cell counts." (PMID 22240797, 2012).
lymphoma (continued). "Irrespective of absolute CD4+ T cell counts, HIV-positive patients who subsequently developed PCNS lymphoma lacked EBV-specific CD4+ T cell function." (PMID 17388662, 2007). "Consistently, lymphomas were Pax5+, B220+, CD43+, AA41+, CD69+ and negative for surface heavy or light chain immunoglobulins, CD5, CD4, CD8, CD23, CD21, BCL6." (PMID 16563162, 2006). "Lymphoma cells are usually positive for: CD7, CD3, CD2, CD8, CD56 and negative for CD4, CD5, CD30." (PMID 39317016, 2024). "In addition, some of the mature lymphomas exhibit GATA3+ TH2 subtype molecular features although, in most cases, are negative for CD4." (PMID 35895495, 2022). "However, in this study, CD4 count and CD4/CD8 did not help to distinguish malignant lymphoma and inflammatory lymphadenopathy, which is in concordance with the previous report by Mhlanga." (PMID 35896979, 2022). "CD4/CD8 subpopulation analyses revealed a heterogeneous CD4/CD8 distribution in both Nipako/ko and Nipawt/wt lymphomas, which was, despite minor variations, similar in both groups with distinct CD4/CD8-double positive, CD4/CD8-double negative, and CD4- and CD8-single positive populations." (PMID 35646639, 2022). "CD4+ T cells are some of the essential non-neoplastic immune cells that affect the survival of DLBCL patients and play a vital role in immune monitoring and influencing lymphoma outcome." (PMID 35711924, 2022). "Unlike the current outcome, experimental work tested the CD4/CD8 ratio in DLBCL samples and concluded that T cell activity may play a role in DBCL lymphoma prognosis." (PMID 35083113, 2022). "However CD4+ T-cell counts decreased upon auto-SCT and their Ki-67 expression levels did not significantly differ between r/r lymphoma patients and those in remission in contrast to Ki-67 expression levels in CD8+ T-cells." (PMID 35794135, 2022). "In addition, it was confirmed that tumor burden, lymphoma type, CAR T-cell dose, CD4/CD8 ratio, and memory phenotype were not significantly distinct between the low and high NOXA expression groups, which ruled out the interference of these factors." (PMID 35370290, 2022). "These lymphomas may be CD4+, CD8+ or double positive, and it is not clear if the lymphoma arises from normal CD20+T cell precursors, or develop CD20 expression aberrantly." (PMID 35951029, 2022). "Lymphoma cells expressed CD3+, CD8+, and CD56+, but not CD4+ or PD‐1." (PMID 33939308, 2021). "In contrast with the lymphoma models, ICBs-CT26 treatment did not induce changes in classical CD8+ nor CD4+ populations, however did induce significant increase of CD4+CD25+FoXP3 and CD4+ Tbet+ subpopulation in the spleen, without changes in CD4+ROR-γt+ subpopulations." (PMID 33623783, 2021). "The results clearly indicated that T cells from HIV+ patients at stages 2 and 3, irrespective of the presence of lymphoma, as well as from EBV+HIV+ patients, have an EBV-specific T cell response of lower quality because they lack mono- and multifunctional CD4+ and CD8+ T cells." (PMID 30337929, 2018). "A beneficial effect of immediate antiretroviral therapy was evident for reductions in rates of TB, Kaposi’s sarcoma, and malignant lymphomas, meanwhile, the significant benefit in the immediate antiretroviral therapy in patients with HIV infection regardless of CD4+ count." (PMID 28056848, 2017). "Although the chemotherapy given to the patient for the lymphoma was not thought to have a role with HS or IRIS, it might delay the possible symptoms of IRIS in such a way preventing the recovery of CD4 counts." (PMID 24987420, 2014). "Neonatal infection with MoMLV leads to accelerated lymphoma onset, increased clonal complexity and lymphoid dissemination, although the tumours retain the characteristic bimodal phenotype seen in the absence of infection (CD8+,CD4+/−,TCRhi)." (PMID 24586197, 2014).
lymphoma (continued). "The pathology report indicated no sign of lymphoma in the left capsule or axillary lymph node; however, the fluid from the area surrounding the left implant showed large atypical cells that were positive for CD30, negative for ALK, and negative for CD2, CD3, CD4, CD7, CD8, CD20, CD56, and TIA-1." (PMID 38256500, 2024). "BM flow cytometry gating on the lymphoma cells confirmed the positive expression of CD2, CD3, CD7, CD8, CD56, T‐cell receptor (TCR) alpha‐beta chains, perforin, granzyme B, and negative for CD34, CD4, CD5, and TCR gamma‐delta chains, consistent with natural killer (NK)/T lymphoma involvement." (PMID 37206287, 2023). "Due to the favorable use of viral load instead of CD4 counts in more recent times, the machine was mostly not utilized, which gave CCC the chance to procure reagents and reactivate the FACS for leukemia and lymphoma diagnostics, without investing in a new machine." (PMID 32374771, 2020). "A small caveat of this study was that the malignant cells do not express CD4 or CD8; thus, they resemble pre–T cell leukemia/lymphoma whereasin vivo ATL cells show a mature regulatory T (Treg)-like phenotype, although expression of CD4 may not be found in all tumor cells of patients with ATL77." (PMID 30854194, 2019). "Further experimentation is required to confirm immunomodulatory role of PD-1 and LAG-3 on bovine T cells, but it seems that these immunoinhibitory receptors might play the major role in CD4+ and CD8+ αβ T-cell subsets, not in γδ T cells, in cattle bearing lymphoma." (PMID 29914540, 2018). "However neither HIV-RNA levels, nor the CD4/CD8 ratio changed during the course of the disease, implying that the HIV-infection was not directly influenced by the reactivation of the EBV-infection or the development of the lymphoma." (PMID 27551290, 2016). "The complex interactions of HIV, CMV and HHV-8- and even HBV could have provided the necessary combination of immune suppression and immune stimulation for the lymphoma genesis to precede and accelerate, even though the HIV-infection was not advanced, as measured by HIV-RNA and CD4 counts." (PMID 27551290, 2016). "Interestingly the representation of PD-1+LAG-3+ co-expressing CD4+ and CD8+ T cells was significantly increased in bovine blood with B-cell lymphoma compared with uninfected animals with uninfected animals as well as in BLV-infected animals but without lymphoma." (PMID 38596123, 2024).